E2F3-IT1 (E2F3 intronic transcript 1)
Synonyms: RBAT1
Gene: Long non-coding RNA gene on chromosome 6 (20,437,821 to 20,440,178, forward strand). Ensembl gene ENSG00000224707.
Diseases named in the same sentence as E2F3-IT1 in open-access papers:
E2F3-IT1 is named in the same sentence as 8 diseases in open-access papers, as found by Europe PMC text mining. Sharing a sentence is not in itself a finding about the gene and the disease.
E2F3-IT1 shares sentences with these, for which no sentence is quoted: retinoblastoma (5 papers); bladder cancer (4); tumor (3); cancer (1); colorectal cancer (1); endometrial carcinoma (1); lymph node metastasis (1); melanoma (1).